ANO4 (anoctamin 4)
Description:
Has calcium-dependent phospholipid scramblase activity; scrambles phosphatidylserine, phosphatidylcholine and galactosylceramide (By similarity). Does not exhibit calcium-activated chloride channel (CaCC) activity (By similarity).
Synonyms: TMEM16D; FLJ34221; FLJ34272; FLJ35277
Tractability: Antibody: UniProt places it where antibodies can reach, with high confidence; its Gene Ontology location is reachable by antibodies, with high confidence; UniProt predicts a signal peptide or a membrane-spanning region.
Gene: Protein-coding gene on chromosome 12 (100,717,244 to 101,128,648, forward strand). Ensembl gene ENSG00000151572.
Subcellular location: Cell membrane
Pathways (Reactome):
Disease: Induction of Cell-Cell Fusion
Transport of small molecules: Stimuli-sensing channels
Gene Ontology:
Molecular function: intracellularly calcium-gated chloride channel activity; chloride channel activity; phospholipid scramblase activity; protein dimerization activity
Biological process: chloride transmembrane transport; monoatomic ion transmembrane transport; phospholipid translocation; plasma membrane phospholipid scrambling
Cellular component: plasma membrane
Genetic constraint (gnomAD): Loss-of-function variants: 59 observed, 127.12 expected, observed/expected ratio (o/e) 0.46, 90% interval 0.38 to 0.58. The upper end of that interval is the gene's LOEUF score, 0.58, which puts it in group 2 of 6, group 1 being the genes least tolerant of losing a copy. Missense variants: 829 observed, 1,119 expected, observed/expected ratio (o/e) 0.74, 90% interval 0.7 to 0.79. Synonymous variants: 328 observed, 384.87 expected, observed/expected ratio (o/e) 0.85, 90% interval 0.78 to 0.93.
Homologues: Orthologues: chimpanzee ANO4 (99% identical), dog ANO4 (99% identical), pig ANO4 (99% identical), rabbit ANO4 (99% identical), macaque ANO4 (98% identical), mouse Ano4 (98% identical), rat Ano4 (98% identical), guinea pig ANO4 (97% identical), tropical clawed frog ano4 (84% identical). Paralogues in human: ANO3 (62% identical), ANO6 (40% identical), ANO1 (40% identical), ANO5 (39% identical), ANO2 (38% identical), ANO7 (34% identical), ANO9 (31% identical), ANO8 (21% identical), ANO10 (20% identical), PPP1R7 (9% identical).
Diseases named in the same sentence as ANO4 in open-access papers:
ANO4 is named in the same sentence as 19 diseases in open-access papers, as found by Europe PMC text mining. Sharing a sentence is not in itself a finding about the gene and the disease. The quoted sentences say what the papers report.
breast carcinoma (4 papers, 2020 to 2022). "A meta-analysis of genome-wide association studies in breast cancer revealed an association with a cluster of genes that is involved in endo-/exocytosis, among them ANO4." (PMID 33800471, 2021). "Indeed, SNPs in the ANO4 gene associate with breast cancer and various brain disorders such as schizophrenia or anxiety disorders." (PMID 33800471, 2021). "In addition, Single-Nucleotide Polymorphisms in the ANO4 gene are associated with breast cancer." (PMID 35207044, 2022).
Hypoglycemia (4 papers, 2020 to 2023). A decreased concentration of glucose in the blood. "During hypoglycemia, the activation of GI neurons in ERαvlVMH neurons is mediated by the calcium-activated chloride channel protein channel encoded by anoctamin 4 (Ano4), which contributes to their depolarization." (PMID 35757435, 2022). "Together, these results identified Ano4 as a key ion channel that mediates the activation of GI-ERαvlVMH neurons evoked by hypoglycemia." (PMID 32358493, 2020). "Hypoglycemia activates GI-ERαvlVMH neurons via the anoctamin 4 channel, and inhibits GE-ERαvlVMH neurons through opening the ATP-sensitive potassium channel." (PMID 32358493, 2020). "In combination with whole-cell patch clamp and RNA-sequencing, we have identified that hypoglycemia activates GI-ERαvlVMH neurons through the opening of anoctamin 4 (Ano4, a chloride channel), and inhibits GE-ERαvlVMH neurons through the opening of the Abcc8-containing KATP channel." (PMID 35619170, 2022). "Genetic disruption of the Ano4 gene in VMH neurons reduced blood glucose and impaired counterregulatory responses during hypoglycemia in mice." (PMID 37261917, 2023).
anxiety disorder (2 papers, 2021 to 2024). A category of psychiatric disorders which are characterized by anxious feelings or fear often accompanied by physical symptoms associated with anxiety. "Polymorphism detection and single nucleotide polymorphism-directed (SNP) genome-wide analysis revealed that ANO4 provides a genetic background for a variety of brain disorders, such as schizophrenia, Alzheimer’s disease and anxiety disorders." (PMID 33800471, 2021). "ANO4 has not been linked to a Mendelian phenotype so far, but genome-wide association studies showed an association between single-nucleotide polymorphisms near ANO4 and various neurological diseases, such as schizophrenia, Alzheimer disease, and anxiety disorder." (PMID 38744284, 2024).
cervical cancer (1 paper, 2022). A primary or metastatic malignant neoplasm involving the cervix. "Overexpression of ANO4 or ANO9 in human cervical cancer cells (HeLa), enhanced constitutive shedding of the growth factor AREG and increased cell proliferation." (PMID 35207044, 2022).
epilepsies (1 paper, 2024). "In summary, we expand the genetic base for both encephalopathic sporadic and inherited fever-sensitive epilepsies and link germline variants in ANO4 to a hereditary disease." (PMID 38744284, 2024).
Epileptic encephalopathy (1 paper, 2024). A condition in which epileptiform abnormalities are believed to contribute to the progressive disturbance in cerebral function. "Here, we identified five de novo and two inherited missense variants in ANO4 (alias TMEM16D) as a cause of fever-sensitive developmental and epileptic or epileptic encephalopathy (DEE/EE) and generalized epilepsy with febrile seizures plus (GEFS+) or temporal lobe epilepsy." (PMID 38744284, 2024).
febrile seizures (1 paper, 2024). "In this paper, we describe seven ANO4 missense variants identified in either sporadic individuals with DEE or EE or families with genetic epilepsy with febrile seizures plus (GEFS+) or temporal lobe epilepsy (TLE)." (PMID 38744284, 2024).
glioblastoma (1 paper, 2020). The most malignant astrocytic tumor (WHO grade IV). "TOP2A, COL4A1 and PXDN were significantly upregulated and ANK3, ARRB1 and ANO4 markedly downregulated in glioblastoma compared to controls." (PMID 32962742, 2020).
tumor (2 papers, 2015 to 2023). "In conclusion, ANO4 expression was upregulated in tumor samples compared to normal kidney tissue." (PMID 36836529, 2023).
cancer (1 paper, 2015). A tumor composed of atypical neoplastic, often pleomorphic cells that invade other tissues. "This notion is supported by the upregulation of the smooth muscle gene Ano4, which corroborates the leiomyosarcomatous nature of the cancer." (PMID 25861239, 2015).
ANO4 also shares sentences with these, for which no sentence is quoted: schizophrenia (2 papers); Alzheimer disease (1); brain disorder (1); Clear Cell Renal Cell Carcinoma (1); Fever (1); generalized epilepsy (1); Hyperglycemia (1); neurological diseases (1); temporal lobe epilepsy (1).